HSPB7 (heat shock protein family B (small) member 7)
Synonyms: cvHsp
Tractability: No criterion of Open Targets' tractability assessment is met for any kind of drug.
Gene: Protein-coding gene on chromosome 1 (16,014,028 to 16,020,597, reverse strand). Ensembl gene ENSG00000173641.
Subcellular location: Cytoplasm; Nucleus; Nucleus, Cajal body
Subcellular location (Human Protein Atlas): Nucleoplasm
Gene Ontology:
Molecular function: protein binding; filamin binding
Biological process: regulation of heart contraction; response to unfolded protein; heart development
Cellular component: cytoplasm; nucleus; actin cytoskeleton; Cajal body
Genetic constraint (gnomAD): Loss-of-function variants: 9 observed, 10.34 expected, observed/expected ratio (o/e) 0.87, 90% interval 0.52 to 1.51. The upper end of that interval is the gene's LOEUF score, 1.51, which puts it in group 6 of 6, group 1 being the genes least tolerant of losing a copy. Missense variants: 246 observed, 248.28 expected, observed/expected ratio (o/e) 0.99, 90% interval 0.89 to 1.1. Synonymous variants: 102 observed, 103.37 expected, observed/expected ratio (o/e) 0.99, 90% interval 0.84 to 1.16.
Homologues: Orthologues: chimpanzee HSPB7 (100% identical), macaque HSPB7 (99% identical), dog HSPB7 (98% identical), mouse Hspb7 (95% identical), pig HSPB7 (95% identical), rabbit HSPB7 (95% identical), rat Hspb7 (94% identical), guinea pig HSPB7 (90% identical), tropical clawed frog hspb7 (64% identical), zebrafish hspb7 (64% identical), Drosophila melanogaster l(2)efl (25% identical), Drosophila melanogaster CG14207 (21% identical), and 14 more. Paralogues in human: HSPB1 (25% identical), HSPB6 (25% identical), HSPB8 (24% identical), CRYAB (24% identical), HSPB2 (24% identical), CRYAA (21% identical), HSPB3 (15% identical), HSPB9 (12% identical).
Diseases named in the same sentence as HSPB7 in open-access papers:
HSPB7 is named in the same sentence as 55 diseases in open-access papers, as found by Europe PMC text mining. Sharing a sentence is not in itself a finding about the gene and the disease. The quoted sentences say what the papers report.
heart failure (14 papers, 2010 to 2026). Inability of the heart to pump blood at an adequate rate to meet tissue metabolic requirements. "The GWAS of NT-proBNP levels identified cardiomyopathy- or heart failure-associated genetic loci (eg, HSPB7/CLCNKA, CDKN1A, TTN, FLNC, and BAG3)." (PMID 41054850, 2025). "When we clustered the results, one PPI cluster for LVEF is dominated by genes previously implicated with dilated cardiomyopathy and heart failure risk (HSPB7, FLNC, ALPK3, CLCNKA), as well as links to the brain via WDR7391–97." (PMID 39670392, 2025). "HSPB7 (or cvHSP) is known to be involved in heart failures and is suspected of acting as a tumor suppressor, associated with renal carcinomas." (PMID 36765939, 2023). "HSPB7 gene variants have been implicated in a range of human cardiovascular diseases including heart failure and dilated cardiomyopathy." (PMID 35548346, 2022). "Among the induced chaperones is HSPB7, a cardiac heat shock protein that is linked to cardiomyopathy in genome-wide association studies and significantly co-occurs with heart failure publications in the literature." (PMID 33116222, 2020). "In the present study, we generated a cardiac-specific inducible HSPB7 knockout mouse and demonstrated that the loss of HSPB7 in cardiomyocytes results in rapid heart failure and sudden death." (PMID 28827800, 2017). "Although rs1739743 and another 11 additional HSPB7 SNPs were further confirmed to be associated with heart failure, the additional SNPs were also found to be intronic or synonymous." (PMID 28827800, 2017). "Recent studies have reported that an intronic single-nucleotide polymorphism (SNP) rs1739843 in HSPB7 is highly associated with heart failure (HF), dilated cardiomyopathy (DCM), and idiopathic DCM in human patients." (PMID 28827800, 2017). "Genome wide association studies identified HSPB7 as a SNP associated risk gene for idiopathic cardiomyopathies and heart failure." (PMID 28973020, 2017). "It is important to note, however, that the original SNP (rs1739843) and subsequent SNPs in HSPB7 that were associated with heart failure were intronic or synonymous." (PMID 28228157, 2017). "Several genome-wide association studies found that SNPs in the HSPB7 gene were strongly associated with idiopathic cardiomyopathies and heart failure." (PMID 24585183, 2014). "GWAS and EWAS defined HSPB7 gene locus as a risk factor to develop DCM or heart failure." (PMID 35281256, 2022). "Our in silico analysis supported an association of HSPB7 with various human cardiovascular pathologies, most notably downregulation associated with various cardiomyopathies, heart failure and atrial fibrillation, and upregulation associated with dilated cardiomyopathy." (PMID 35548346, 2022). "Additionally, several single-nucleotide polymorphisms of HSPB7 have been identified to be associated with heart failure caused by cardiomyopathy in human patients." (PMID 28827800, 2017). "Colocalisation with heart failure implicates 23 shared loci and bioinformatic analysis prioritises genes including HSPB7, CAMK2D, ALDH2, ENG, and YWHAE." (PMID 41760662, 2026). "Here we used whole-exome sequencing and bioinformatics on human patient data to identify 3 genes (API5, HSPB7, and LMO2) suggestively associated with heart failure that were also predicted to play a broader role in disease aetiology." (PMID 35548346, 2022). "HSPB7 has been also indicated as a candidate gene involved in heart development and cardiac failure." (PMID 35281256, 2022). "Eight genes (TTN, BAG3, GRK5, HSPB7, MTSS1, ALPK3, NMB, and MMP11) supported by at least 2 independent lines of in silico evidence were implicated in the cardiac morphogenesis and heart failure development." (PMID 31554410, 2019). "HSPB7 warrants some further discussion as it has been identified in studies of both heart failure and DCM." (PMID 28228157, 2017).
heart failure (continued). "Consistent with the role of HSPB7 in development, both global and cardiac-selective KO in mice are lethal at the embryonic stage, with embryos characterized by smaller hearts, thinner left ventricular walls and features indicative of heart failure." (PMID 35281256, 2022). "We identified a subset of three genes (API5, HSPB7, and LMO2) predicted to play a broader role in heart failure aetiology, and undertook in vivo phenotypic assessment in zebrafish." (PMID 35548346, 2022). "In our study, inhibition of TBX5 was shown to dysregulate several genes such as DES, NKX2-5, ACTC1, MYH6, ATP2A2 and HSPB7, which further contributed to ICM-related diseases such as failure of heart and degeneration of heart." (PMID 32423033, 2020). "NKX2-5, HSPB7 and BCL2L1 were also involved in failure of heart." (PMID 32423033, 2020). "This same locus was also identified in a GWAS of DCM, which could reflect either the physiological importance of HSPB7 and/or the likelihood that DCM patients were a subset of the heart failure patients." (PMID 28228157, 2017).
cardiomyopathy (10 papers, 2017 to 2025). A disease of the heart muscle or myocardium proper. "In a zebrafish model, HSPB7 was involved in early post-damage processing of large cytoskeletal proteins and the loss of HSPB7 function was accompanied by an increased damaged protein load, protein aggregation and a risk of cardiomyopathy." (PMID 31323898, 2019). "By using a TALEN-mediated knockout of HSPB7, the same group recently showed that loss of HSPB7 increases the susceptibility of adult mutant zebrafish for cardiomyopathy due to impaired protein homeostasis serving as another proof of the initial GWAS findings." (PMID 29911105, 2018). "Using an HSPB7 inducible-conditional knockout (CKO) model approach, here we demonstrate that the loss of HSPB7 leads to cardiomyopathy and arrhythmic sudden death." (PMID 28827800, 2017). "However, the multiple observations of HSPB7 polymorphisms in HF and cardiomyopathy suggests a common genetic basis for these related phenotypes." (PMID 33467574, 2021). "HSPB7, sometimes referred to as the “cardiovascular Hsp” due to its high cardiac expression, is an sHsp that has attracted interest as a possible susceptibility locus for cardiomyopathy and HF." (PMID 33467574, 2021). "Noteworthy, mutations in BAG3, the obligatory partner of HSPB8, cause cardiomyopathy, besides neuropathy and myopathy, and mutations in other HSPBs (HSPB5, HSPB6, and HSPB7) also associate with cardiac pathology." (PMID 40467930, 2025). "Although this is the first study demonstrating Hsp mutations in PPCM, genetic variation in HSPB5, HSPB7 and HSPD1 has been reported in other cardiomyopathies." (PMID 33467574, 2021). "Given the cardiomyopathy and sudden death observed in HSPB7 CKO mice, we speculated that the normal electrophysiological activities were disturbed in the HSPB7 mutant hearts." (PMID 28827800, 2017).
breast carcinoma (5 papers, 2016 to 2021). "With regard to the relationship between HSPB7 and ERK signaling pathway, Naderi found HSPB7 overexpression in breast cancer cells reduced the level of p-ERK." (PMID 33097082, 2020). "Hspb7, Mb, Cox7a1, Fbp2, and Scara5 have all previously been identified as tumor suppressor genes in breast cancer, non-small cell lung cancer, gastric cancer, sarcoma, and hepatocellular carcinoma, wherein they can suppress tumor cell invasion, proliferation, and migration." (PMID 34194323, 2021). "Another interesting observation from the present study is that several HSPs were downregulated in all breast cancer subtypes: DNAJB4, DNAJC18, HSPA12A, HSPA12B, HSPB2, HSPB6, and HSPB7." (PMID 29954368, 2018). "MDA‐MB‐231 (breast cancer), DU‐145 (prostate cancer), and A549 (non‐small‐cell lung cancer) cell lines were employed for colony forming assays in view of the fact that they all have low levels of SRARP and HSPB7 expression." (PMID 29577611, 2018). "Reduction of Hsf1 reduces HSPB7 and inhibits EMT and tumorigenesis in mouse breast cancer models." (PMID 27876705, 2016).
dilated cardiomyopathy (3 papers, 2020 to 2025). Cardiomyopathy which is characterized by dilation and contractile dysfunction of the left and right ventricles. "Heart HSPB7 expression was largely downregulated in association with various cardiac disease conditions, except for dilated cardiomyopathy in which HSPB7 was found to be upregulated in two independent studies." (PMID 35548346, 2022). "For example, mutations in JUP, DSP, PKP2, DSG2, DSC2, CTNNA3, CDH2, or PLN (all of them more abundant in LV) predominantly lead to arrhythmogenic right ventricular cardiomyopathy, and mutations in MYH7, HSPB7, NEXN and MYPN (also all more abundant in LV) lead to dilated cardiomyopathy." (PMID 32291283, 2020).
melanoma (3 papers, 2018 to 2024). A malignant, usually aggressive tumor composed of atypical, neoplastic melanocytes. "Using an in silico cohort of IFN-treated melanoma tissues, we validated a differentially expressed 9-gene core of DEGs, out of which four genes had a predictive power for efficacy: WFDC1, HSPB7, HSF1, and MT2A." (PMID 35269844, 2022). "While there were no data on the role of HSPB7 in melanoma, HSF1 was shown to be upregulated in melanoma due to the loss of FBX7, and was shown to be involved in regulating the metastatic potential." (PMID 35269844, 2022).
myocardial infarction (3 papers, 2017 to 2022). Gross necrosis of the myocardium, as a result of interruption of the blood supply to the area, as in coronary thrombosis. "Despite being the most potent suppressor of sHSP against the aggregation of the mutated huntingtin protein, HSPB7 was reported to be a potential early biomarker of myocardial infarction and an independent risk factor for acute coronary syndrome." (PMID 28827800, 2017). "HSPB7 has also been detected in plasma, with HSPB7 plasmatic concentrations apparently higher in subjects and mouse models of myocardial infarction from 3 up to 24 h after the onset of symptoms." (PMID 35281256, 2022). "HSPB7 (cvHSP) is selectively expressed in cardiac muscle and assumed as an early (1-3h) biomarker of myocardial infarction." (PMID 28973020, 2017). "A dramatic increase in HSPB7 is detected in the heart and blood plasma immediately after myocardial infarction." (PMID 28827800, 2017).
renal cell carcinoma (3 papers, 2014 to 2024). "For example, HSPB7, a member of the small heat shock protein family, has been implicated as a tumour suppressor in renal cell carcinoma (RCC), where it is commonly downregulated." (PMID 39367275, 2024). "Furthermore, the only available publication on HSPB7 in cancer concluded that this gene has a tumor suppressor function in renal cell carcinoma and is epigenetically silenced by hypermethylation in this disease." (PMID 29577611, 2018). "In order to identify genes involved in renal carcinogenesis, we analyzed the expression profile of renal cell carcinomas (RCCs) using microarrays consisting of 27,648 cDNA or ESTs, and found a small heat shock protein, HSPB7, to be significantly and commonly downregulated in RCC." (PMID 24585183, 2014). "Based on the analysis of microarray data of 15 clear cell renal cell carcinomas, we found HSPB7 to be significantly and commonly downregulated in RCC." (PMID 24585183, 2014).
atrial fibrillation (2 papers, 2022 to 2025). A disorder characterized by an electrocardiographic finding of a supraventricular arrhythmia characterized by the replacement of consistent P waves by rapid oscillations or fibrillatory waves that vary in size, shape and timing and are accompanied by an irregular ventricular response. "The research found that serum HSP levels (including HSPB1, HSPA1, HSPB7, and HSPD1) lacked clinical value in predicting postoperative atrial fibrillation (PoAF)." (PMID 40786071, 2025).
endometrial carcinoma (2 papers, 2018 to 2023). A malignant tumor arising from the epithelium that lines the cavity of the uterine body. "A study also showed that HSPB7 was downregulated in endometrial carcinoma (EC) and influenced EC cell proliferation and metastasis via the PI3K/AKT/mTOR signaling pathway (Xing, Wu & Wang, 2023)." (PMID 38084139, 2023).
Hypertension (2 papers, 2020 to 2024). The presence of chronic increased pressure in the systemic arterial system. "The lead GWAS variant, rs1048238 is a common SNP within the 3′ UTR of HSPB7, a chaperone protein that is highly expressed in heart and skeletal muscle and has been associated with hypertension in a recent GWAS39,40." (PMID 31988292, 2020).
ovarian carcinoma (2 papers, 2018 to 2020). A malignant neoplasm originating from the surface ovarian epithelium. "Our study used the Kaplan-Meier method and univariate Cox regression analysis to show that CH25H, HSPB7, and PPM2C correlated with ovarian cancer patients that had the worst prognoses." (PMID 33381581, 2020).
sarcoma (2 papers, 2018 to 2021). A usually aggressive malignant neoplasm of the soft tissue or bone. "The fact that in this study a relatively higher HSPB7 expression was observed in sarcoma may be explained by a common mesodermal origin for all musculoskeletal lineages." (PMID 29577611, 2018). "In addition, SRARP and HSPB7 showed significant copy number gains in only three cancer types, namely cervical cancer, sarcoma, and glioblastoma with gains of 0.15, 0.14, and 0.07 copies, respectively (P < 0.001)." (PMID 29577611, 2018).
acute coronary syndrome (1 paper, 2013). Signs and symptoms related to acute ischemia of the myocardium secondary to coronary artery disease. "Differential expression of Hspb7 proteins, which localize within the cytosol and associate with myofibrils in skeletal and cardiac muscle cells, has been associated with conditions such as sporadic heart failure and acute coronary syndrome." (PMID 23967293, 2013).
advanced heart failure (1 paper, 2019). Patients with advanced heart failure have severe limitations, experiences symptoms even while at rest and are mostly bedbound patients. "Genetic variants in HSPB7 have been associated with advanced heart failure and systolic dysfunction." (PMID 31323898, 2019).
cardiac arrhythmia (1 paper, 2017). Any disturbances of the normal rhythmic beating of the heart or MYOCARDIAL CONTRACTION. "The electrocardiogram showed cardiac arrhythmia with abnormal conduction in the HSPB7 mutant mice before death." (PMID 28827800, 2017).
dystrophin deficiency (1 paper, 2021). "Furthermore, the potential use of distinct chaperones such as cardiovascular heat shock proteins (HSP), HSPB7, HSPB5 (αBC), HSP70 (HSPA) and HSP90 (HSPC) as dystrophin deficiency disease markers for secondary pathological changes or for the evaluation of novel treatments was also recently proposed." (PMID 34445659, 2021).
filaminopathies (1 paper, 2025). "Thus, the data presented uncover the molecular mechanisms underlying some filaminopathies associated with mutations in the 24th immunoglobulin-like domain playing an important role in filamin dimerization and its interaction with HspB7." (PMID 40564978, 2025).
folate deficiency (1 paper, 2019). A nutritional condition produced by a deficiency of FOLIC ACID in the diet. "Thirdly, genes with an opposite expression pattern in folate deficiency and repletion cell lines: SORBS2, DCN, SLFN11, RUNX3, GALC, and HSPB7." (PMID 30836646, 2019).
hyperlipidemia (1 paper, 2022). "In our study, we demonstrate that advanced hyperlipidemia over-regulates HSPB1, HSPB7, HSP90-α (by both mass spectrometry and immunologic assay), and HSP90-β, while HSP60’s spectral abundance was found to be down-regulated." (PMID 36232476, 2022).
muscular dystrophy (1 paper, 2017). Muscular dystrophy (MD) refers to a group of more than 30 genetic diseases characterized by progressive weakness and degeneration of the skeletal muscles that control movement. "HSPB7 upregulation is also found in the muscular dystrophy-affected diaphragm, indicating that HSPB7 levels are induced under stress conditions." (PMID 28484965, 2017).
Obesity (1 paper, 2024). Accumulation of substantial excess body fat. "Although we did not investigate BAT in the present study, the observation that Hspb7 similarly increases in a distinct VAT depot using a different rodent model of obesity represents a compelling reason to understand the role of this gene in mediating AT dysfunction." (PMID 39348460, 2024).
osteoporosis (1 paper, 2020). A condition of reduced bone mass, with decreased cortical thickness and a decrease in the number and size of the trabeculae of cancellous bone (but normal chemical composition), resulting in increased fracture incidence. "The present study provides new insight into the molecular basis of osteoporosis and implied that HSPB7 might be used as a potential diagnostic marker and therapeutic target for osteoporosis." (PMID 33097082, 2020). "As expected, we found the protein expression of HSPB7 was significantly increased in OVX mice, which suggested the potential involvement of HSPB7 in the pathogenesis of osteoporosis." (PMID 33097082, 2020). "Moreover, ectopic bone formation in nude mice and osteoporosis mice model was used to investigate the effect of HSPB7 on osteogenesis in vivo." (PMID 33097082, 2020). "More experimental studies are needed to further explore the role of HSPB7 in osteoporosis." (PMID 33097082, 2020). "We hypothesized that HSPB7 might be aberrantly expressed in osteoporosis model." (PMID 33097082, 2020).
osteosarcoma (1 paper, 2018). A usually aggressive malignant bone-forming mesenchymal neoplasm, predominantly affecting adolescents and young adults. "However, osteosarcoma cell line U‐2 OS showed a relatively higher baseline HSPB7 expression at a −ΔCT of −8.37 (±0.24)." (PMID 29577611, 2018).
stomach adenocarcinoma (1 paper, 2019). "In the stomach adenocarcinoma dataset, strong positive correlations in gene expression were identified between members of the small HSP family, including HSPB2, HSPB5 (CRYAB), HSPB6, HSPB7 and HSPB8, as well as the HSP40 family member DNAJB5, with superoxide dismutase (SOD3)." (PMID 30578123, 2019).